ESR1 (estrogen receptor 1)
Diseases named in the same sentence as ESR1 in open-access papers (continued):
Sharing a sentence is not in itself a finding about the gene and the disease.
breast cancer (continued). "ADELA (NCT06382948) is a phase III trial, where elacestrant combined with everolimus is compared to elacestrant alone in the ER+/HER2− advanced breast cancer population with ESR1-mutated tumors that have progressed on ET and CDK4/6i." (PMID 40244377, 2025). "Liquid biopsy enables the detection of resistance mutations, such as ESR1 mutations in hormone therapy-resistant breast cancer or HER2 mutations in trastuzumab-resistant cases, allowing for timely modifications in treatment strategy." (PMID 40486595, 2025). "Research has discovered that the abnormal expression of the ESR1 gene is strongly linked to the prognosis of breast cancer." (PMID 40149497, 2025). "The presence of Estrogen receptor 1 (ESR1) mutations in hormone receptor–positive breast cancer is associated with resistance to hormonal therapies." (PMID 40764849, 2025). "In the phase 3 VERITAC-2 trial, vepdegestrant improved PFS compared to fulvestrant in patients with previously treated HR+/HER2-negative advanced breast cancer containing ESR1 mutation." (PMID 41226406, 2025). "Metastatic, therapy-resistant ER-positive breast cancers driven by ESR1 mutations represent a significant clinical challenge and account for a substantial number of breast cancer-related deaths." (PMID 40641933, 2025). "The transcriptional landscape in elderly patients with breast cancer is dominated by concomitant somatic mutations, such as ESR1 and PIK3CA." (PMID 40361341, 2025). "Several new SERDs are currently under development to overcome the limitations of the existing SERD, including its poor activity against ESR1 mutation-positive breast cancer and the necessity of intramuscular injection because of its poor bioavailability." (PMID 40227585, 2025). "Several mechanisms are involved in the resistance to endocrine therapy (ET) in estrogen receptor (ERα)-positive breast cancer (BC), including acquired mutations of ERα gene (ESR1)." (PMID 40518539, 2025). "Rad1901, an orally available SERD also retains efficacy in the presence of ESR1 mutations, and was recently FDA-approved for patients with ESR1 mutated advanced ER+ breast cancer based on the positive results of the phase III EMERALD trial." (PMID 38978585, 2024). "For example, ESR1 variant rs140068132 which is thought to have originated in Indigenous Americans, is protective for breast cancer risk." (PMID 38836758, 2024). "Estrogen receptor (ESR1) ligand mutations have been linked to endocrine resistance, osteoporosis, and breast cancer." (PMID 39457593, 2024). "ESR1 mutations are rare in primary breast cancer and develop in metastases during endocrine therapy." (PMID 39272884, 2024). "Some variants at the ESR1 locus have been reported to exhibit ancestry-specific association with breast cancer risk." (PMID 38836758, 2024). "The impact of previous treatments, particularly evident in investigations of ESR1 mutations among breast cancer patients undergoing aromatase inhibitor therapy, has the potential to obscure results." (PMID 38791037, 2024). "For example, detecting ESR1 mutations in HR+ breast cancer can predict resistance to aromatase inhibitors, guiding a switch to therapies such as fulvestrant." (PMID 39484719, 2024). "Two of the analyzed SNVs were functional breast cancer risk SNVs located upstream of the ESR1 gene (rs2046210, rs9383590), and one an intronic ESR1 SNV (rs9340799), previously associated with infertility and an implantation defect." (PMID 39200122, 2024). "Although targeting of ER+ breast cancer patients with endocrine therapy (ET) is currently a standard treatment, mutations of ESR1 is the essential driver of ET resistance." (PMID 38215156, 2024).
breast cancer (continued). "In an analysis of genes in breast cancer bone metastasis, the ESR1, GATA3, and MLPH genes were associated with an increased incidence of bone metastasis with an AUC of 0.702, 0.489, and 0.651, respectively." (PMID 38791037, 2024). "ESR1 mutations account for 20–40% of the resistance in metastatic breast cancer cases receiving endocrine therapy." (PMID 39063972, 2024). "In women, activation of estrogen receptor-alpha (ERα), encoded by the Esr1 gene, plays a crucial role in the initiation, development, and progression of breast cancer." (PMID 39682141, 2024). "In this study, we employed breast cancer cells expressing commonly observed ESR1 mutations (Y537N and Y537S) and wt ER counterparts and evaluated their growth in the presence/absence of estrogen (E2)." (PMID 38519482, 2024). "The estrogen receptor (ER, ESR1) is expressed in two-thirds of all breast cancer, and under endocrine stress, somatic ESR1 mutations arise in approximately 30% of cases that result in endocrine resistance." (PMID 39207954, 2024). "ESR1 mutations have been identified as a common mechanism of endocrine therapy resistance in ER+ breast cancer." (PMID 38339371, 2024). "Urinary AMPA was associated with hypomethylation in the ESR1 promoter, which has been linked to breast cancer risk and endocrine disruption." (PMID 39200696, 2024). "Simultaneously, DEHP has been reported to not only mediate drug resistance by activating the vinculin/aryl hydrocarbon receptor (AhR)/ERK signaling pathway but also enhance susceptibility to breast cancer by upregulating the Esr1/HDAC6 pathway in female rats." (PMID 38341560, 2024). "In the past decade, LB analysis has been employed in multiple clinical trials to investigate the prevalence of ESR1 mutations in ER+ ​breast cancer." (PMID 40027941, 2024). "This experimental venue would be able to clarify the interaction between the immune system, ESR1 mutated breast cancers, and the signaling between these two actors." (PMID 38519482, 2024). "This paradigm now applies to breast cancer as well, with detection of an estrogen receptor 1 (ESR1) mutation in liquid biopsy being associated with a benefit from elacestrant therapy." (PMID 40027147, 2024). "From breast cancer GWAS, multiple variants near ESR1 have been associated with breast cancer of all subtypes as well as ER− tumors." (PMID 38836758, 2024). "ESR1 mutations have been recently shown to be a key mechanism of resistance to ET in ER+ ​breast cancer, making the detection of these mutations critical for monitoring patient treatment." (PMID 40027941, 2024). "The novel oral SERD Elacestrant has demonstrated promising results in treating breast cancer patients with resistance to endocrine therapy due to ESR1 gene mutations." (PMID 38212842, 2024). "For instance, while one report demonstrated that Hdac3 ablation promoted degradation of Esr1 mRNA (i.e. the gene encoding ERα) in breast cancer cells, others have shown that HDAC3 inhibition promotes Esr1 expression." (PMID 39261913, 2024). "Based on the results from the EMERALD trial, elacestrant was approved by the FDA for treating ER+ HER2− advanced breast cancer with the ESR1 mutation and prior treatment with at least one line of ET." (PMID 38339371, 2024). "Y537S and D538G are the two most frequently detected ESR1 mutations in metastatic breast cancers resistant to endocrine therapy." (PMID 39702552, 2024). "Mutations in the ligand-binding domain of the ESR1 gene are observed in resistant breast cancer cells." (PMID 38791941, 2024). "Camizestrant also has shown promising efficacy in treating ESR1 mutations in breast cancer, as evidenced by its significant improvement in progression-free survival (PFS) compared to fulvestrant." (PMID 38800404, 2024). "Elacestrant is becoming increasingly available, and testing for ESR1 mutations in advanced breast cancer with either liquid or tissue biopsy is currently recommended by clinical guidelines." (PMID 38869741, 2024).
breast cancer (continued). "In ER+ breast cancer, ESR1 mutations have become a key mechanism of resistance to endocrine therapy; therefore, CDKN1A becomes a very promising target for cancer treatment." (PMID 38254989, 2024). "Over seventy percent of breast cancers are classified by their expression of the nuclear hormone receptor estrogen receptor alpha (ERα), encoded by the ESR1 gene." (PMID 38978585, 2024). "Conversely, in advanced breast cancers, even extensive ESR1 gene mutations and ER protein modifications are incapable of counteracting the excessive genomic damage." (PMID 39329990, 2024). "Variants at the ESR1 locus were among the first to be associated with breast cancer risk in GWAS and are associated with breast cancer in multiple populations including Chinese, Indian, Nigerian, African American, Malaysian, Latina/Hispanic." (PMID 38836758, 2024). "Studies have shown that if the ESR1 gene is overexpressed in breast cancer cells, the risk of postmenopausal women developing ER-positive breast cancer increases." (PMID 39206151, 2024). "ESR1 mutations play a crucial role in the development of endocrine therapy resistance in breast cancer." (PMID 38339371, 2024). "During treating metastatic estrogen receptor (ER) positive breast cancer with Aromatase inhibitors, ESR1 mutations are a common mechanism of hormone therapy resistance." (PMID 37799727, 2023). "Mutations in the ESR1 gene affecting the hormone binding domain of its product ERα are associated with Notch activation in breast cancer cell lines." (PMID 37568775, 2023). "In breast cancer, recent clinical trials are evaluating new SERDs to counter hormone resistance acquired with AI, notably via ESR1 mutations." (PMID 37924026, 2023). "ESR1 mutations occur in up to 20% of recurrent breast cancers arising in patients treated with anti-estrogen therapies and occur almost exclusively in patients treated with aromatase inhibitors." (PMID 36597146, 2023). "We assessed ESR1 mutations in circulating tumor DNA (ctDNA) for impact on outcome to taxane-based chemotherapy in advanced breast cancer patients." (PMID 37226020, 2023). "For example, ESR1 encodes an ER and ligand-activated transcription factor, which plays a key role in breast cancer, endometrial cancer and osteoporosis." (PMID 36307127, 2023). "The mechanism of endocrine resistance in ER+ breast cancer includes the loss of ERα expression, the mutation of the ESR1 gene, and the activation of alternative signaling pathways, such as HER2." (PMID 37894401, 2023). "In this study, we used this method to analyze ESR1 mutations in mRNA extracted from FF tissues of 212 ER-positive primary breast cancers." (PMID 37174098, 2023). "ESR1 mutations were measured with an LNA-clamp ddPCR of cDNA extracted from FF tissues of 212 patients with primary breast cancers." (PMID 37174098, 2023). "In mice, the combination of fulvestrant and palbociclib or everolimus inhibits tumor growth in breast cancers harboring D538G or Y537S ESR1 mutations." (PMID 36980614, 2023). "Then, we used this method to analyze ESR1 mutations in fresh-frozen (FF) tissues of primary breast cancer." (PMID 37174098, 2023). "Although ESR1 mutations are rare in primary breast cancers, they are frequently reported in patients with recurrent breast cancer who have previously received endocrine therapy." (PMID 37370935, 2023). "This ESR1 gene is coding for the estrogen receptor alpha monomer, an established risk factor and promising clinical biomarker in breast cancer pathophysiology." (PMID 36703164, 2023). "Meta-analysis of the effects of ESR1 mutations in breast cancer revealed that D538G is the most frequently detected mutation and is associated with poor relapse free survival." (PMID 36909339, 2023). "Genetic variants at 6q25.1, containing the ESR1 gene, were found to be associated with breast cancer susceptibility." (PMID 36831182, 2023).
breast cancer (continued). "For instance, the ESR1 gene carries single-nucleotide polymorphisms (SNPs) linked to estrogen resistance, breast cancer, mineral bone density, and cardiovascular risk factors." (PMID 37760622, 2023). "ESR1 mutations, particularly of residues associated with the ligand binding domain, while rare in primary breast cancer, have an increased frequency in metastatic or recurrent disease." (PMID 37662839, 2023). "The ESR1 gene encodes for ERα and the histological protein expression closely reflects the gene expression pattern; in most aggressive breast cancers, a loss of the ERα has been attributed to methylation of the CpG island in the ESR1 gene promoter." (PMID 36978627, 2023). "We further analyzed all available plasma-cfDNA and CTC-derived gDNA samples from the three breast cancer patients (Pt#11, Pt#12, Pt#13) that developed metastasis at different time points for ESR1 and PIK3CA mutations." (PMID 36690653, 2023). "Among patients with recurrent breast cancer after treatment with adjuvant AI, ESR1 mutations are found in 4–5% of cases." (PMID 38003387, 2023). "Genome-wide association studies (GWAS) have demonstrated that single nucleotide variants (SNVs) in chromosomal region 6q25.1, which contains the ESR1 gene, are significantly associated with breast cancer susceptibility." (PMID 36831182, 2023). "The PNA-LNA PCR clamping method is a highly sensitive and minimally invasive assay for polyclonal ESR1 mutation detection in the ctDNA of patients with breast cancer." (PMID 37370935, 2023). "Accordingly, rs9383590 has been suggested to be a functional SNV in the ESR1 locus that accounts for its association with breast cancer risk." (PMID 36831182, 2023). "In this case, the second surgical sample had a pathogenic ESR1 D538G mutation known to be associated with endocrine therapy resistance in breast cancer." (PMID 36125633, 2023). "It potently inhibited cell proliferation in a panel of ER + breast cancer cell lines, including the cell lines containing ESR1 mutations (Y537 and D538)." (PMID 37580832, 2023). "ESR1 mutations are common in patients with advanced breast cancer previously treated with hormonal therapy and are associated with resistance to hormonal treatments." (PMID 37176102, 2023). "In HR + breast cancer, it is now clearly established that circulating ESR1 mutations emergence is a mechanism of resistance to AI in the metastatic setting, with an incidence ranging from 30 to 50% depending on the series." (PMID 37924026, 2023). "Estrogen Receptor 1 (ESR1) is associated with breast cancer, endometrial, and other types of cancer." (PMID 37590265, 2023). "Although pivotal in breast cancer biology and evolution, ESR1 and PIK3CA mutations clinically are simplistically dichotomized as mutated or wild type." (PMID 37784176, 2023). "Hormone therapy resistance causing mutations in ESR1 occur in 12–18% of metastatic ER+ breast cancers." (PMID 37264081, 2023). "Then, 212 primary breast cancers were analyzed, find that 27 patients (12.7%) had 28 ESR1 mutations." (PMID 37174098, 2023). "In preclinical and clinical studies, it has been observed that ESR1 mutations appear in the early stages of breast cancer development." (PMID 37835383, 2023). "Recently, studies on liquid biopsy demonstrated the subclonal origin of different mutations (i.e., ESR1) in pretreated advanced ER + breast cancer and their implication for response to therapy." (PMID 36831647, 2023). "Overall, this innovative procedure of follow-up liquid biopsy to monitor ESR1 mutation can represent a giant leap for the personalization of endocrine therapy in breast cancer." (PMID 37958343, 2023). "rs9383590 has been suggested to be a causal SNV for the observed associations of polymorphisms in and around the ESR1 locus with an increased breast cancer risk." (PMID 36831182, 2023). "ESR1: This gene encodes a receptor that plays a key role in breast cancer, endometrial cancer and osteoporosis." (PMID 37468832, 2023).
breast cancer (continued). "Paclitaxel have shown therapeutic effect on advanced breast cancer patients with ESR1 mutations, which indicate HGDrug provided insight into the potential mechanism for known drug-disease (side effect) interactions." (PMID 37956212, 2023). "With regard to ESR1 mutations, in HR+ breast cancer, HER2-zero tumors harbored the highest percentage of mutations than HER2-positive and HER2-low tumors in our NGS database." (PMID 37264417, 2023). "For instance, alterations in ERS1 (Estrogen Receptor 1) gene, which is associated to oestrogen resistance, has been found in circulating tumor DNA of a cohort of patients with breast cancer." (PMID 37542343, 2023). "The breast cancer-associated enhancer 6 kb from the TSS is bound by ESR1, consistent with the observation that MYB is regulated by the Estrogen Receptor." (PMID 36688700, 2023). "Breast cancers expressing Estrogen Receptor alpha (ERα, encoded by the ESR1 gene) are dependent on estrogen-induced signaling for proliferation, and they are highly susceptible to an array of hormonal interventions targeting this pathway." (PMID 37318638, 2023). "The expression of ESR1 mutations in breast cancer is more common in hormone receptor-positive metastatic breast cancers (MBC)." (PMID 37174098, 2023). "ESR1 mutations in breast cancer are one of the mechanisms of resistance to aromatase inhibitors (AI)." (PMID 37174098, 2023). "Several clinical investigations have substantiated that mutation of ESR1 was associated with metastasis in breast cancer." (PMID 37900162, 2023). "The ESR1 gene encoding ERα is perhaps the most clinically relevant gene in breast cancer biology, with key roles as a target of systemic therapy, a predictive and prognostic marker and a determinant of the molecular subtype." (PMID 36831182, 2023). "An ongoing active phase III randomized trial (ELAINE-3) will evaluate the efficacy and safety of this combination against fulvestrant + abemaciclib in ESR1-mutated breast cancer." (PMID 37860199, 2023). "The incidence of ESR1 mutation in primary breast cancer is less than 1%, while it is more than 20% in aromatase inhibitor-resistant breast cancer patients." (PMID 37900137, 2023). "The acquisition of ligand-independent ESR1 mutations during aromatase inhibitor therapy in metastatic ER + breast cancer was a common mechanism of hormonal therapy resistance." (PMID 37580832, 2023). "It is noteworthy that novel agents are being explored in hormone-resistant breast cancers that harbor ESR1 mutations, including giredestrant, proxalutamide, and enobosarm." (PMID 38239650, 2023). "For example, ESR1 activating mutations are rarely present in primary ER+ breast cancer, even in those 15–20% of patients that show intrinsic resistance to hormonal therapies." (PMID 36909339, 2023). "Here, we analyzed the association of two noncoding SNVs in a putative enhancer region upstream of the ESR1 gene with the risk, age at onset, clinically and molecularly relevant characteristics and prognosis of breast cancer." (PMID 36831182, 2023). "In canine mammary tumors (CMTs), the ESR1 gene encodes for ERα, and represents a major target gene for miR-18a and miR-18b, previously found to be overexpressed in mammary carcinomas." (PMID 36978627, 2023). "The ESR1 gene encodes ERα and represents an important target mRNA for miR-18a and miR-18b, described as overexpressed oncogenes in canine mammary carcinomas." (PMID 36978627, 2023). "While several studies on ESR1 mutation have been reported for breast carcinoma, very few data are available on endometrial carcinoma." (PMID 37924026, 2023). "In this study, we explore the therapeutic potential of bromodomain and extraterminal domain (BET) inhibition to target ESR1 mutation–induced “transcriptional addiction” in ER+ breast cancer." (PMID 35881485, 2022). "With the introduction of next-generation sequencing (NGS) technology in genomic research, ESR1 mutations have been re-analyzed in samples from metastatic ER+ breast cancer." (PMID 35501333, 2022).